EGFR (epidermal growth factor receptor)
Diseases named in the same sentence as EGFR in open-access papers (continued):
Sharing a sentence is not in itself a finding about the gene and the disease.
asthma (continued). "In vivo rodent models confirm the importance of EGFR in asthma." (PMID 23577003, 2013). "EGFR is amongst other RTKs being probed as potential drug targets for asthma." (PMID 23577003, 2013). "The PDGFR and epidermal growth factor receptor (EGFR) groups of TK receptors have gained interest as plausible therapy targets for respiratory afflictions, as these receptors have been shown to perform important functions in persistent tissue repair in respiratory fibrosis, bronchitis, and asthma." (PMID 40136649, 2025). "Therefore, the EGFR tyrosine kinase inhibitory resistance pathway may provide a useful biomarker for H. cuspidatus asthma treatment efficacy." (PMID 35572723, 2022). "Therefore, we speculate that lonicerin may exert anti-asthma effects by affecting the EGFR signaling cascade." (PMID 36618942, 2022). "Moreover, preclinical animal models have also demonstrated a strong role for EGFR in asthma." (PMID 33123005, 2020). "Therefore, inhibiting EGFR tyrosine kinase activity may be beneficial to the treatment of hypersecretory diseases, such as asthma, chronic obstructive pulmonary disease (COPD), and bronchiectasis." (PMID 31426531, 2019). "In our study, we have found that there are significant differences in the expression of genes (SYK, PI3K, and EGFR) and the concentration of cytokines between dust mite-induced asthma and healthy controls, suggesting that EGFR, SYK, and PI3K may be involved in dust mite-induced pediatric asthma." (PMID 30406061, 2018). "The involvement of EGFR in the airway response to diesel exhaust could potentially be of even more importance in subjects with asthma and COPD in which this receptor tyrosine kinase has been indicated to play a major role in the inflammatory, proliferative and remodelling processes." (PMID 18460189, 2008). "Lonicerin alleviates asthma by exerting anti-inflammatory and immunomodulatory effects through inhibition of the SRC/EGFR pathway." (PMID 41599256, 2026). "This regulation of cbl-b, EGFR, AKT1, and MAPK1 suggests new potential therapeutic targets for asthma treatment." (PMID 40264707, 2025). "Since SR1001 blocked exaggerated EGFR activation in patients with asthma by suppressing autophosphorylation and JNK/STAT/Akt activation, we propose a cross-talk between the MCC and EGFR signaling." (PMID 40131242, 2025). "Additional miRNAs like hsa-miR-451a, miR-203a-3p, and miR-27a-5p were tied to asthma-related genes including MYC, EGFR, and BMI1, highlighting their involvement in airway inflammation and remodeling." (PMID 40806181, 2025). "PTGS2, IL10, CTSB, JAK2, and MTOR were significantly downregulated in alveolar lavage fluid with increasing asthma severity, while MMP9, GSK3B, BCL2, EGFR, and CCND1 were upregulated." (PMID 40160461, 2025). "Through literature search, we found that the research on IL6, EGFR, and HIF1A to asthma was relatively richer compared with these of other targets." (PMID 38590639, 2024). "Although the molecular mechanisms by which OBE produces its anti-inflammatory action are not clear, our data suggests that it likely involves inhibiting the EGFR, ERK1/2 and AKT signaling pathway, which is an important pathway in the asthma phenotype." (PMID 38584568, 2024). "In our study, we employed a network pharmacology approach to prioritize seven predicted targets (AKT1, VEGFA, EGFR, SRC, MAPK3, MMP9, MAPK1) of baicalein for asthma treatment, and confirmed its high binding affinity to these targets through molecular docking." (PMID 38178132, 2024). "More importantly, we showed the efficacy of baicalein in reducing airway inflammation and airway remodeling in an OVA-induced asthma mouse model and verified the involvement of the VEGF and EGFR signaling pathways in the therapeutic effect of baicalein." (PMID 38178132, 2024). "It has been reported that the secretion of EGF increases in asthma and EGF can induce the activation of the EGFR-AKT signalling pathway." (PMID 38093206, 2023).
asthma (continued). "For the molecular docking, the four target genes, AKT1, EGFR, VEGFA, and HSP90AB, were selected based on KEGG analysis results in the asthma pathway." (PMID 36836768, 2023). "Using Gromacs-2022.04, we simulated the molecular dynamics (MD) of a 100 ns protein-ligand complex for EGFR, ALB, MAPK8, ESR1, and SRC, respectively, which are typical core targets for allergic rhinitis and asthma." (PMID 37781715, 2023). "In this study, we constructed the PPI network; IL6, CASP3, EGFR, MAPK8, ESR1, CCND1, and PPARG were found to be the core genes of YPF in treating asthma." (PMID 36105239, 2022). "Lastly, miR-142 has been shown to be overexpressed in ASM cells derived from an asthma rat model and inhibits TGF-β expression via epidermal growth factor receptor (EGFR) signalling, leading to decreased collagen I and collagen III expressions." (PMID 34359876, 2021). "There are extensive studies focusing on the relation among EGFR, VEGFA and asthma pathophysiology, which describe airway remodeling, airway hypermucus secretion, as well as immunological responses of airway inflammation." (PMID 33968984, 2021). "Regulation of LOX-5, EGFR, and IKK by RU can be utilized to develop anti-inflammatory drugs where both NSAIDs-related side effects, like asthma, and cytokine storm in different types of chronic inflammation can be reduced." (PMID 34885978, 2021). "We observed fewer EGFR + and ST2 + ciliated epithelial cells in asthma and TGFβ + secretory epithelial cells in controls after UPM exposure." (PMID 34168212, 2021). "We showed changes in the expression of EGFR + and ST2 + on epithelial cells with ciliated phenotype in asthma, and TGFβ + on epithelial cells with secretory phenotype in controls after UPM exposure." (PMID 34168212, 2021). "Gefitinib, an inhibitor of Epidermal growth factor receptor (EGFR) tyrosine kinase, suppresses allergic airway inflammation by inhibiting phosphatidyl inositol-3 kinase (PI3K)/Akt signaling in mouse model of asthma." (PMID 32733254, 2020). "In asthma for example, enhanced expression of EGF/EGFR was observed in the bronchial epithelium, airway glands, smooth muscle and basement membrane of asthmatic individuals, and correlated well with sub-epithelial basement membrane thickening." (PMID 31675376, 2019). "Receptor tyrosine kinases are of interest in this communication spectrum because the family archetype is epidermal growth factor receptor (EGFR), which through pleiotropic roles in cellular function, is unsurprisingly incriminated in asthma." (PMID 30423826, 2018). "Of particular interest, EGFR-expression appears to be increased in the airway epithelium of asthmatics, smokers and patients with COPD and CF, and the pulmonary expression of EGFR and CXCL8 correlates in patients with severe asthma." (PMID 26147224, 2015). "Furthermore, this study utilized network pharmacology to identify pivotal asthma treatment targets for YKS, including AKT1, TNF, IL1B, EGFR, IFNG, IL4, CASP3, and PTGS2." (PMID 40420184, 2025). "Finally, we obtained 7 predicted targets of baicalein for asthma treatment, namely AKT1, VEGFA, EGFR, SRC, MAPK3, MMP9, MAPK1." (PMID 38178132, 2024). "We used an OVA-induced asthma mouse model to verify that the expression of VEGFA, EGFR and the phosphorylation of ERK are involved in the pathogenesis of asthma, and that baicalein can inhibit the expression of VEGFA, EGFR and the phosphorylation of ERK in these mice." (PMID 38178132, 2024). "From a mucus production perspective, the upregulation of EGFR (even though it did not pass the significance threshold) has been shown to be involved in mucin production by airway goblet cells in asthma." (PMID 39594673, 2024). "Further validation by reverse transcription quantitative polymerase chain reaction (RT-qPCR) and western blotting analysis revealed that the VEGF and EGFR signaling pathways involving VEGFA, MAPK1, MAPK3, and EGFR were inhibited by baicalein in the asthma mouse model." (PMID 38178132, 2024).
asthma (continued). "Core target analysis showed that SZYQD may directly or indirectly affect asthma through potential targets, such as AKT, IL-6, TNF-α, and EGFR." (PMID 38093206, 2023). "The top 10 highest degree of targets were EGFR, JAK1/2, MAPK14, VEGF, SRC, mTOR, PI3K, and GSK3B, which might be the critical targets of HHAE for the treatment of asthma." (PMID 36408342, 2022). "Among these components, caffeic acid might be recognized as an essential active compound in H. cuspidatus containing multiple targets, including STAT3, EGFR, and PIK3CA, that contributed to treating asthma." (PMID 35572723, 2022). "Our subsequent molecular docking showed that each bioactive compounds (quercetin, wogonin, luteolin, naringenin, and kaempferol) of MGMD has favorable binding abilities with STAT3, PTGS2, JUN, VEGFA, EGFR, and ALOX5, further arguing the potential molecular mechanism of action of MGMD in asthma." (PMID 33968984, 2021). "In clinical aspects, a positive correlation between EGFR and MUC5AC expression was confirmed using bronchial mucosal biopsy specimens from human subjects divided into a healthy control group and a group with asthma." (PMID 33217964, 2020). "The EGF/EGFR is a critical signaling pathway in the pathogenesis of asthma, and both EGF and EGFR levels have been shown to be consistently increased in both human asthma and in animal models of asthma." (PMID 33123005, 2020). "Meanwhile, authors have investigated that PM increased the expression of amphiregulin (AREG) in human bronchial epithelial cells (HBECs) and further induced inflammation and mucus hypersecretion via the EGFR-PI3Kα-AKT/ERK pathway, which is known to promote the development and exacerbation of asthma." (PMID 32411804, 2020). "Intracellular ROS generation in airway epithelial cells by HDM allergen or viral RNA sensor activation thus share, through confluent signaling, pleiotropic operational elements (thrombin, ADAM 10, EGFR, TLR4) fundamental to the progression of allergic sensitization and asthma exacerbations." (PMID 29542272, 2018). "The fact that these allergic airway inflammatory responses and more importantly the EGFR-triggered signaling perturbations were significantly attenuated by AG1478, confirms the critical role played by EGFR in mediating the pathophysiology of asthma." (PMID 28855674, 2017). "In asthma, overexpression of EGF/EGFR correlates with disease severity and epithelial injury." (PMID 26057128, 2015). "Consequently, combined with the enrichment of the EGFR signaling pathway in the KEGG pathway analysis above, we speculate that the possible target suggesting lonicerin for asthma treatment may be Src/EGFR pathway." (PMID 36618942, 2022). "Firstly, increasing studies have demonstrated non-HLA antibodies such as Col-V and EGFR involved in the IL-17–related pathways in different pulmonary diseases (and may contribute to severe asthma)." (PMID 34760922, 2021). "In addition, while ovalbumin-induced asthma and inhaled TNF-α-induced airway inflammation in rats lead to increased EGFR expression and goblet cell production in the AE, these effects are abrogated by prior treatment with EGFR inhibitor BIBX1522." (PMID 34248677, 2021). "The important role that EGFR plays in asthma is also underscored by studies showing that tyrosine kinase inhibitors such as gefitnib, erlotinibin and AG1478, inhibit both EGFR phosphorylation and asthma features such as cellular influx and airway remodeling and AHR." (PMID 31675376, 2019). "Thus, it appears that the expression of these gene (SYK, EGFR, PI3K), which are involved in the PI3K-AKT pathway, may be connected with the secretion level of cytokine in asthma, especially in dust-mite induced pediatric asthma." (PMID 30406061, 2018).
asthma (continued). "Thus, whilst potential inhibition of the PI3Kδ, ERK1/2 and NFκB effector molecules may be of some benefit as a therapeutic strategy asthma, it is more likely that a greater therapeutic margin would be gained by blocking upstream targets such SFK or EGFR." (PMID 28855674, 2017). "However, clinical studies of EGFR inhibitors for asthma have not been reported." (PMID 38178132, 2024). "Loss of the superficial epithelial layer, preferential destruction of ciliated cells, and over expression and activation of EGFR with increases in growth factors, including TGFβ, are found in the majority of asthma suffers; even occurring in mild, early, and non-fatal asthma." (PMID 38529406, 2024). "Besides transgelin-2, some targets (i.g., ESR1, EGFR, CASP3, and SRC) may be important for the anti-asthmatic effect of glycyrrhizin, and some signaling pathways (i.g., SRC/EGFR signaling pathway) are also promising research directions for improving asthma." (PMID 37711178, 2023). "Finally, asthma-related Th2 cytokines such as IL-4, IL-5, and IL-13 can induce EGFR expression, while cytokines produced by activated eosinophils such as IL-3 and IL-5 can induce TGF-α production by epithelial cells and subsequently induce mucins production through EGFR signaling." (PMID 34248677, 2021). "Therefore, upstream inhibition, at the level of Src or EGFR, appears to be more effective than blockade of the individual downstream pathways involving ERK1/2, PI3Kδ/Akt or the transcriptional factor NFκB – a finding that may have important clinical implications in the treatment of asthma." (PMID 28855674, 2017). "In another study, using the OVA-induced rat asthma model reported that ovalbumin sensitization and challenge resulted in airway remodeling, epithelial cell proliferation, and goblet cell hyperplasia with increased HB-EGF secretion, but not EGFR expression in the airway epithelium." (PMID 33217964, 2020).
atherosclerosis (106 papers, 2008 to 2026). A disease characterized by the build-up of fatty material and calcium deposition in the arterial wall resulting in partial or complete occlusion of the arterial lumen. "In either case, knowing that EGFR regulates EC-associated inflammation is highly relevant when considering the role of the latter in cardiovascular diseases, such as atherosclerosis or coronary artery diseases." (PMID 38129563, 2023). "Another potential mechanism mediating EGFR signaling is related to the finding that the redox state of plasma is more oxidized in patients with risk factors for atherosclerosis." (PMID 24132149, 2013). "EGFR has been recently implicated in vascular pathophysiological processes associated with excessive remodeling and atherosclerosis." (PMID 18664296, 2008). "EGFR deficiency could limit lipid uptake, attenuate the inflammatory response, and impede the development of atherosclerosis." (PMID 38920980, 2024). "In addition to its prominent role in the development of several cancers, EGFR has been currently implicated in vascular pathophysiological processes associated with excessive remodeling and atherosclerosis." (PMID 18664296, 2008). "EGFR, a member of the ErbB receptor tyrosine kinase family, plays a critical role in atherosclerosis development." (PMID 41544081, 2026). "KEGG pathway analysis identified 94 signaling pathways, among which the most significant included the PI3K-Akt signaling pathway, pathways in cancer, EGFR tyrosine kinase inhibitor resistance, and fluid shear stress and atherosclerosis." (PMID 41515972, 2025). "In this study, EGFR, VEGFA, HSP90AA1, SRC, HIF1A, CXCR4 and IGF1R were identified as key hub targets, which linked anthocyanins with atherosclerosis." (PMID 40478326, 2025). "HB-EGF has been found in human atherosclerotic plaques: EGFR inhibition leads to a reduction of T cell migration and cytokines expression, limiting atherosclerosis development." (PMID 39966897, 2025). "The KEGG pathway enrichment analysis highlighted 20 key signaling pathways significantly influenced by EERM, including the PI3K-Akt signaling pathway, lipid metabolism and atherosclerosis, and EGFR TKI resistance." (PMID 39808649, 2025). "It has also been reported that disruption of toll-like receptor 4 (TLR4)/EGFR signaling pathway reduced inflammatory activity and foam cell formation, resulting in alleviating atherosclerosis." (PMID 40478326, 2025). "The interaction of ASGR1 with epidermal growth factor receptor (EGFR) activates the extracellular signal-regulated kinase (ERK) pathway, which has been linked to inflammatory regulation and atherosclerosis." (PMID 38539180, 2024). "Mouse-specific atherosclerosis mechanisms identified in the aorta include signaling by insulin receptor, EGFR, ERBB2, NGF, and TGF-beta signaling, axon guidance, VEGF and VEGFR pathways, and Tap63 and DeltaNp63 pathways." (PMID 38060277, 2023). "The enrichment analysis of the 171 UC targets showed that 26, 23 and 33 proteins are involved in AGE-RAGE, EGFR and atherosclerosis signaling pathways, respectively." (PMID 38196993, 2023). "It has also been shown that smooth muscle cells in atherosclerosis show increased EGFR downstream signaling and EGFR phosphorylation." (PMID 37699925, 2023). "ERRFI1 can also act on EGFR expressed in intimal smooth muscle cells of human atherosclerotic plaques and plays a key role in the development of atherosclerosis." (PMID 37699925, 2023). "miR-7-5p is also observed to have a casual effect on EGFR, which is involved in the development of atherosclerosis and inflammatory response." (PMID 37569355, 2023). "As a receptor of TSP-1, epidermal growth factor receptor (EGFR) has been reported to be involved in vascular pathophysiology and pathogenesis of atherosclerosis in macrophages." (PMID 35001873, 2022).